MET (MET proto-oncogene, receptor tyrosine kinase)
Diseases named in the same sentence as MET in open-access papers (continued):
Sharing a sentence is not in itself a finding about the gene and the disease.
sarcoma (continued). "Sorafenib, regorafenib, lenvatinib, and anlotinib, all of which have activity against VEGFR, PDGFR, RET, c-KIT and FGFR, and cabozantinib, which has a different target profile (VEGFR, MET, AXL, and RET), have all shown some clinical benefit in sarcoma." (PMID 34944614, 2021). "Although MET fusions are uncommon drivers of sarcoma, a TFG-MET fusion has been reported in a patient with an infantile spindle cell sarcoma with neural features." (PMID 34863095, 2021). "We evaluated intra-tumoral kinetics by FLT-PET imaging, to c-MET inhibitors and MDM2 inhibitors in patients with multiple types of sarcoma." (PMID 32106426, 2020). "Of note, in contrast to Ewing sarcoma, rhabdomyosarcomas express the RTKs EGFR and MET, the latter with specific oncogene addiction, placing RON–IGF1R interactions in these sarcomas before a distinct RTK network background." (PMID 32272784, 2020). "Knock down of the hepatocyte growth factor receptor, c-MET, significantly enhanced the lethality of [602 + doxorubicin] in sarcoma cells, arguing that the immediate-early activation of this receptor tyrosine kinase was a compensatory survival signal." (PMID 32983965, 2020). "These sarcoma subtypes were chosen as they are known to harbor specific alterations that result in ALK and/or MET activation." (PMID 31665941, 2019). "Our goal was to determine the prevalence of the three major mechanisms of MET activation, i.e., MET gene amplification, and MET as well as HGF protein overexpression in clinically relevant sarcoma entities." (PMID 25844809, 2015). "6/9 tumors (67%) were simultaneously positive for MET and HGF, i.e., 3/5 undifferentiated pleomorphic sarcomas, and 3/4 angiosarcomas showed 2+ staining for both proteins (p<0.001, Chi Square and Fisher’s exact)." (PMID 25844809, 2015). "With more than 400 sarcoma and GIST cases included in our study this is the largest investigation on fluorescence in situ hybridization for the detection of MET amplifications in these tumors up to now." (PMID 25844809, 2015). "Combined overexpression of HGF and c-MET have been observed in numerous sarcomas, and HGF can activate c-MET in an autocrine manner in these tumors." (PMID 25098767, 2014). "Previously, in sarcoma cells treated with the multi-kinase inhibitor pazopanib and the HDAC inhibitors sodium valproate or entinostat we also observed, in drug-resistant cells, that c-MET as well as ERBB1 had become activated." (PMID 32983965, 2020). "The CREATE trial is an example of a biomarker-driven basket trial, leveraging on the demonstrated biological activity of crizotinib in preclinical work and applying that to sarcoma subtypes with known genetic alterations resulting in the upregulation of ALK and/or MET." (PMID 31665941, 2019). "CCS is a sarcoma affecting tendons and aponeuroses and is characterized by a chromosomal translocation resulting in the generation of a EWSR1-ATF1 fusion gene and subsequent aberrant overexpression of MET." (PMID 31665941, 2019). "Based on our findings angiosarcomas and undifferentiated pleomorphic sarcomas rather than other frequent adult-type sarcomas should be considered for clinical trials with MET inhibitors." (PMID 25844809, 2015). "To examine whether pazopanib has the similar effects on other sarcoma cell line, we used Asra-Eps, which was our established epithelioid sarcoma cell line driven by HGF/c-MET signaling." (PMID 24946937, 2014). "Interestingly, MACC1 was able to induce c-MET expression in the U-2OS sarcoma cell line but not in non-cancerous human umbilical vein endothelial cell (HUVEC), indicating that MACC1 requires the presence of c-MET-specific transcription factors." (PMID 39580452, 2024). "For a subset of angiosarcomas and for clear cell sarcomas we could not obtain valid data on MET immunohistochemistry." (PMID 25844809, 2015).
sarcoma (continued). "On the other hand, we could clearly demonstrate that 96% of all sarcomas in our cohort do not harbor any significant increase in MET gene copy numbers (“MET negatives”)." (PMID 25844809, 2015). "Besides, miR-939-3p could neither further enhance sarcoma cell proliferation nor regulate AP-1 activity or MET expression, when BATF2 was knocked down by a large amount of siRNA in HT-1080 cells." (PMID 38420020, 2024). "Interestingly, MET was expressed but not phosphorylated in a genetically modified Ewing sarcoma cell line with shRNA-silencing of the specific Ewing sarcoma oncogene EWS-FLI1, which links the EWS-FLI1 oncogene to distinct scatter factor RTK expression patterns of pediatric sarcomas." (PMID 32272784, 2020). "Still, compared to its scatter-factor relative MET, RON and its unique ligand MSP (macrophage stimulating protein; also known as macrophage stimulating 1) remain understudied and have not been investigated in sarcomas." (PMID 32272784, 2020). "Among all clinical trials listed at clinicaltrials.gov for MET and HGF inhibitors four studies are open explicitly for patients with sarcomas and there are multiple studies open to patients with not further specified solid tumors, which could include also soft tissue sarcomas (June 2014)." (PMID 25844809, 2015).
papillary renal cell carcinoma (37 papers, 2012 to 2025). "MET variants in the N‐lobe of the kinase domain, found in hereditary papillary renal cell carcinoma, require ligand stimulation to promote cell transformation, in contrast to other RTK variants." (PMID 39980226, 2025). "Trisomy of chromosome 7, amplification and/or somatic activating mutations, and the associated overexpression of MET are frequent driver events in the carcinogenesis of sporadic papillary renal cell carcinoma." (PMID 40564049, 2025). "MET variants in the N‐lobe of the kinase domain, found in hereditary papillary renal cell carcinoma, still require ligand stimulation to promote cell transformation, in contrast to other RTK variants." (PMID 39980226, 2025). "The evidence for it playing a role in oncogenesis is mounting as not only its somatic mutations have been found in many cancers, germ line c-MET point mutations are present in subset of tumors such as papillary renal cell carcinoma." (PMID 26097886, 2015). "Mutations in the MET gene were subsequently described in hereditary and sporadic papillary renal cell carcinomas." (PMID 25887320, 2015). "Indeed, in a subgroup analysis of a phase II trial for papillary renal cell carcinoma, the objective response rate and disease control rate were 50% and 100%, respectively, for patients with the germline point mutations of MET." (PMID 35690785, 2022). "Following the discovery of mutations in the tyrosine kinase domain of MET in hereditary and sporadic papillary renal cell carcinomas, MET mutations have also been found in up to 30% of cancers of unknown primary origin." (PMID 25887320, 2015). "Importantly, genetic alterations, which generate ligand-independent MET mutants have been found in both hereditary and sporadic papillary renal cell carcinomas and involve mutations in the tyrosine kinase domain of MET." (PMID 24378750, 2013). "In hereditary papillary renal cell carcinoma (HPRCC), the hepatocyte growth factor receptor (MET) receptor tyrosine kinase (RTK) mutations recorded to date are located in the kinase domain and lead to constitutive MET activation." (PMID 39980226, 2025). "Many MET mutations have also been described in hereditary papillary renal cell carcinoma (HPRCC) and non‐small‐cell lung cancer (NSCLC), with for each cancer‐specific types of mutations." (PMID 39980226, 2025). "This is the first systematic review and meta-analysis to bring together the available data on the efficacy and safety of MET inhibitors in patients with advanced papillary renal-cell carcinoma." (PMID 38139411, 2023). "Due to the poor effectiveness of currently available therapies for hereditary papillary renal cell carcinoma, it is critical to understand how MET inhibitors affect it." (PMID 35402508, 2022). "The activity of foretinib was demonstrated in a phase II trial in patients with advanced papillary renal cell carcinoma (PRCC), especially in those with germline MET mutations." (PMID 27172793, 2016). "MET p.H1094R has previously been described in papillary renal cell carcinoma." (PMID 33898318, 2021). "Interestingly, a case of a family with HPRCC was reported with a novel germline missense mutation of c-MET with a histological pattern consisting in multiple adenomas and papillary renal cell carcinomas with focal clear cells and a mixture of type I and type II pattern." (PMID 32751108, 2020). "In human cancer, three different means of MET activation have been reported: HGF-dependent (autocrine or paracrine system); overexpression of MET (oligomerization of MET causes reciprocal activation); and activating point mutations (such as hereditary papillary renal cell carcinoma)." (PMID 29890660, 2018). "A biostatistics and microarray survey in PTC and papillary renal cell carcinomas detected concomitant overxpression of LRRK2 and the MET proto-oncogene." (PMID 25923053, 2015).
papillary renal cell carcinoma (continued). "MET expression is significantly correlated with PD-L1 positivity in clear cell renal cell carcinomas but not in papillary renal cell cancers." (PMID 29137273, 2017).
uveal melanoma (33 papers, 2012 to 2025). A melanoma derived from melanocytes of the uveal tract. "In contrast, however, adrenocortical carcinoma (ACC), CHOL, ESCA, KICH, LAML, mesothelioma (MESO), pheochromocytoma and paraganglioma (PCPG), TGCT, THYM, and uveal melanoma (UVM) virtually barely had MET mutations." (PMID 33178590, 2020). "GNAQ and GNA11 lead mutations generate an upregulation of MET factor (related to the appearance of liver metastasis by uveal melanoma)." (PMID 28573105, 2017). "These mutations can lead to upregulation of MET, which is implicated in proliferation and migration of uveal melanoma cells." (PMID 28103611, 2017). "Furthermore, we observed a significantly higher copy number of the MET gene in association with enhanced MET transcript levels in cell lines harboring Gnaq/11 Q209 mutations in a dataset of 10 uveal melanoma cell lines from the DepMap project." (PMID 38360887, 2024). "As for miR-34a-5p, it has been shown to inhibit the growth and migration in uveal melanoma cell lines by targeting c-Met (MET Proto-Oncogene, Receptor Tyrosine Kinase)." (PMID 40869968, 2025). "The STRING analysis performed in plasma samples of uveal melanoma patients for miR-454-3p showed that the MET and HGF molecules were the target proteins that mostly interact with miR-454-3p (p value: 0.000129)." (PMID 38914847, 2025). "HGF induces uveal melanoma cell proliferation and survival, which produces resistance to MET inhibitors, such as crizotinib and cabozantinib, in metastatic uveal melanoma tumors." (PMID 37576814, 2023). "Much lower levels of s-MET were detected in healthy donors and metastasis-free uveal melanoma patients, than in those with metastatic disease." (PMID 30513872, 2018). "In this context HGF and its receptor c-MET have been involved in tumor invasiveness and metastatic progression in different types of tumors, also including uveal melanoma." (PMID 22267972, 2012). "Potentially, other liver metastasis interaction for uveal melanoma could be achieved through the c-MET Tyrosine kinase receptor (MET Proto-Oncogene) and Insulin-Like Growth Factor 1 Receptor (IGF-1R)." (PMID 38732371, 2024). "It has been reported that c-MET is expressed on uveal melanoma cells and the combination of c-MET inhibitors like crizotinib with PKC inhibitors may be useful in treating patients with uveal melanoma." (PMID 37576814, 2023). "Moreover, uveal melanoma cell lines representing high expression of MET/EGFR possessed higher migration potential." (PMID 31638339, 2019). "In particular, preclinical evidence suggests that liver metastasis from uveal melanoma may be strongly dependent on the MET pathway." (PMID 28103611, 2017). "Cabozantinib showed clinical activity in patients with metastatic melanoma, including uveal melanoma, although it is unclear whether this is exclusively due to the inhibitory effects on c-MET, as cabozantinib also inhibits VEGF receptors and the AXL receptor tyrosine kinase." (PMID 30513872, 2018). "Knockdown of MET, as well as selective inhibitors of EGFR, decreased proliferation of high MET‐expressing uveal melanoma cells." (PMID 31638339, 2019). "PHA-665752, while suppressing the phosphorylation of c-MET, significantly inhibited the PI3K/AKT pathway activity and motility of uveal melanoma cells in vitro, and tumor growth in nude mice." (PMID 30513872, 2018). "A previous report indicated that HGF enhances migration of uveal melanoma cells and our present study also indicate that the HGF/c-MET axis plays a role in driving invasion." (PMID 22267972, 2012). "The cell growth of uveal melanoma cell lines was described as not being sensitive to the MET inhibitor crizotinib and MET downregulation, while crizotinib prevents their metastasis potential." (PMID 31040922, 2019). "The uveal melanoma recently gave another model in which MET is required for cell migration and invasion, and not proliferation." (PMID 31040922, 2019).
myeloma (32 papers, 2009 to 2025). "It has also been shown that c‐MET gene knock‐down in myeloma cells increased the cells' susceptibility to bortezomib and doxorubicin." (PMID 36825580, 2023). "Amuvatinib exhibited tumoricidal activity in myeloma cells which was associated with inhibition of MET signaling." (PMID 24326130, 2013). "The hepatocyte growth factor/c-MET pathway has been implicated in the pathobiology of multiple myeloma, and c-MET inhibitors induce myeloma cell apoptosis, suggesting that they could be useful clinically." (PMID 28337527, 2017). "Further, combination strategies with other anti-myeloma therapeutics, including proteasome inhibitors, may be an attractive option, since c-MET activation may be associated with clinical drug resistance." (PMID 28337527, 2017). "Anlotinib has been shown to directly target c-Myc in multiple myeloma, and reverse resistance through targeting the c-MET/MYC/AXL axis in NSCLC." (PMID 40316534, 2025). "A phase II study with the c-MET inhibitor tivantinib in patients with relapsed/refractory multiple myeloma (MM) has been recently reported." (PMID 40520181, 2025). "The basal phosphorylation level of c‐MET and the downstream signal transducers varied in myeloma cells." (PMID 36825580, 2023). "Our earlier study showed that an antagonist against HGF, that is, NK4, also inhibited HGF/c‐MET signaling and anti‐angiogenic activity in a mouse MM xenograft model, indicating the growth dependency of myeloma cells on HGF/c‐MET." (PMID 36825580, 2023). "MET has also been described as a potential therapeutic target for multiple myeloma (MM), where Akt/mTOR is a crucial signaling component through which Met protects multiple myeloma cells from chemotherapy-induced growth inhibition and apoptosis." (PMID 36430388, 2022). "In several glioma cell lines and in a multiple myeloma cell line, the reduction of MET expression by shRNA-mediated knockdown or antisense oligodeoxynucleotides enhanced the effect of temozolamide, paclitaxel or doxorubicin, in reducing cell survival." (PMID 33526881, 2021). "A phase II study with the c-MET inhibitor Tivantinib has been recently reported in patients with relapsed/refractory multiple myeloma." (PMID 30642077, 2019). "Numerous studies have instead clearly established a key role for the HGF/c-MET axis in promoting myeloma cells aggressiveness." (PMID 30642077, 2019). "HGF and c-MET expression at the mRNA and protein levels has been found in most myeloma cell lines and primary samples." (PMID 28337527, 2017). "We conducted a phase II study with the c-MET inhibitor tivantinib in patients with relapsed, or relapsed and refractory myeloma whose disease had progressed after one to four prior therapies." (PMID 28337527, 2017). "The orally bioavailable ATP-competitive MET inhibitor amuvatinib, currently in trials for the treatment of solid tumors, has been shown to result in cell death in myeloma cells known to be dependent on HGF/MET signaling." (PMID 27655636, 2016). "It binds with high affinity to MET and displays in vitro inhibitory activity on human myeloma cells harboring a MET-HGF autocrine loop." (PMID 28548076, 2014). "Collectively, these data demonstrate MET’s pivotal role in myeloma cell biology and underscore the importance of MET targeting as a therapeutic strategy in MM." (PMID 24326130, 2013). "Cell death and growth as well as MET signaling pathway were assessed in amuvatinib treated primary myeloma cells and cell lines." (PMID 24326130, 2013). "Expression of both HGF and MET has been demonstrated in most myeloma cell lines and primary patient samples." (PMID 24326130, 2013).